REDIC1 (regulator of DNA class I crossover intermediates 1)
Description:
Involved in recombination, probably acting by stabilizing recombination intermediates during meiotic crossover formation. Required for normal germline development and fertility. Required for meiotic progression, complete chromosomal synapsis and crossover formation. Binds double-stranded DNA. However, also binds branched DNA molecules, such as those containing a D-loop or Holliday junction structure. Probably not required for formation of DNA double-strand breaks (DSBs). Also binds RNA in an RNA structure-independent manner, with a preference for binding 3'-UTR regions of mRNAs; may stabilize bound RNAs.
Synonyms: C12orf40; FLJ40126; HEIP1; HEL-206; HEL-S-94
Tractability: No criterion of Open Targets' tractability assessment is met for any kind of drug.
Gene: Protein-coding gene on chromosome 12 (39,626,167 to 39,908,300, forward strand). Ensembl gene ENSG00000180116.
Subcellular location: Chromosome
Subcellular location (Human Protein Atlas): Golgi apparatus; Cytosol
Gene Ontology:
Molecular function: protein binding
Cellular component: chromosome
Genetic constraint (gnomAD): Loss-of-function variants: 22 observed, 25.77 expected, observed/expected ratio (o/e) 0.85, 90% interval 0.61 to 1.22. The upper end of that interval is the gene's LOEUF score, 1.22, which puts it in group 5 of 6, group 1 being the genes least tolerant of losing a copy. Missense variants: 559 observed, 514.94 expected, observed/expected ratio (o/e) 1.09, 90% interval 1.01 to 1.16. Synonymous variants: 166 observed, 172.85 expected, observed/expected ratio (o/e) 0.96, 90% interval 0.85 to 1.09.
Homologues: Orthologues: chimpanzee REDIC1 (98% identical), macaque REDIC1 (91% identical), pig REDIC1 (67% identical), mouse Redic1 (53% identical), rat Redic1 (52% identical).
Diseases named in the same sentence as REDIC1 in open-access papers:
REDIC1 is named in the same sentence as 2 diseases in open-access papers, as found by Europe PMC text mining. Sharing a sentence is not in itself a finding about the gene and the disease. The quoted sentences say what the papers report.
Infertility (1 paper, 2023). "Thus, our findings reveal a crucial role for C12ORF40/REDIC1 in meiotic crossover formation by stabilizing the recombination intermediates, providing prospective molecular targets for the clinical diagnosis and therapy of infertility." (PMID 37612290, 2023). "Thus, we identified C12ORF40/REDIC1 as a novel recombination protein essential for meiotic crossover formation and confirmed that the loss of function of this gene could result in infertility in both humans and mice." (PMID 37612290, 2023). "Redic1 KI female mice did not produce any pups during the two months of crossing with WT males, and thus they are infertile." (PMID 37612290, 2023).
REDIC1 also shares sentences with these, for which no sentence is quoted: prostate carcinoma (1 paper).